SSTR2 (somatostatin receptor 2)
Diseases named in the same sentence as SSTR2 in open-access papers (continued):
Sharing a sentence is not in itself a finding about the gene and the disease.
atypical carcinoid tumor (1 paper, 2022). A carcinoid tumor characterized by a high mitotic rate, often associated with the presence of necrosis and nuclear pleomorphism. "Scans with Krenning scores of ≤2 (N=5) were seen in tumors with no SSTR2 expression in 80% of cases and a single atypical carcinoid tumor with SSTR2 expression in 10% of tumor cells." (PMID 35198446, 2022). "Interestingly, while all tumors with scans showing Krenning scores 1 or 2 or no uptake had no expression of SSTR2, the atypical carcinoid tumor with no uptake on 68Ga-DOTATATE PET scan did show strong SSTR2 expression in 10% of the tumor cells." (PMID 35198446, 2022).
autoimmune disease (1 paper, 2025). A disorder resulting from loss of function or tissue destruction of an organ or multiple organs, arising from humoral or cellular immune responses of the individual to their own tissue constituents. "SSTRs, particularly the SSTR2 subtype, have been increasingly recognized as potential molecular targets in the imaging of chronic inflammation and autoimmune diseases." (PMID 41375754, 2025).
autoimmune thyroid disease (1 paper, 2020). Inflammatory disease of the thyroid gland due to autoimmune responses leading to lymphocytic infiltration of the gland. "In addition, patients with pre-existing autoimmune thyroid disease might be at a higher risk for accelerated destruction of the SSTR2-positive thyroid tissue following PRRT." (PMID 33551992, 2020).
benign prostatic hyperplasia (1 paper, 2022). A non-cancerous nodular enlargement of the prostate gland. "Consistently, endogenous CORT was overexpressed in PCa samples (compared with benign-prostatic-hyperplasia) and correlated with key clinical (i.e., metastasis) and molecular (i.e., SSTR2/SSTR5 expression) parameters." (PMID 36361790, 2022).
Bladder Paraganglioma (1 paper, 2023). A benign or malignant extra-adrenal sympathetic paraganglioma arising from the urinary bladder. "The result of postoperative pathology was immediate-risk functional bladder paraganglioma (T2N0M0, Stage II) concomitant with urothelial papilloma, and the immunohistochemistry results of PPGL were positive for Ki-67 (15%), SDHB, CgA, and SSTR2." (PMID 36741690, 2023).
brain infarct (1 paper, 2021). "Accordingly, SST and a related peptide, cortistatin-14, and the synthetic SSTR2, SSTR3, and SSTR5 agonist octreotide significantly reduce brain infarct size in a middle cerebral artery occlusion model." (PMID 34803662, 2021).
cholestasis (1 paper, 2024). Impairment of the bile flow caused by obstruction within the liver, or outside the liver in the bile duct system. "Though few significant differences in biliary development were found between Tgm2−/− and WT mice in normal feeding, deficiency of Tgm2 in mice caused the damage of the hallmarks of normal biliary cells such as OPN, acTUB, TGR5, and SSTR2 and even more severe cholestasis in DDC‐induced DR." (PMID 38623945, 2024). "These reprogrammed cells displayed acTUB‐marked primary cilia, CK19‐marked mature biliary, and SSTR2‐marked functional biliary, indicating that hepatocytes can participate in DR by hepatocytic metaplasia in DDC‐induced cholestasis." (PMID 38623945, 2024).
clear cell renal cell carcinoma (1 paper, 2022). "In the literature concordant data exist with our own experience of variable vascular PSMA and SSTR2 expression in clear cell renal cell carcinoma (unpublished data), as the morphologically closest differential diagnosis." (PMID 35546652, 2022).
epilepsy (1 paper, 2018). A brain disorder characterized by episodes of abnormally increased neuronal discharge resulting in transient episodes of sensory or motor neurological dysfunction, or psychic dysfunction. "The expression of the subtypes SSTR1 and SSTR2 has been documented in rats in different disease models, such as the epilepsy model." (PMID 29522573, 2018).
Epstein-Barr virus infection (1 paper, 2021). An infection that is caused by Epstein-Barr virus. "Taken together, these findings imply that EBV infection induces SSTR2 expression in nasopharyngeal epithelial cells through expression of the latent oncoprotein LMP1 and activation of the NF-κB and MEK signaling pathways." (PMID 33402692, 2021). "EBV infection of cultured primary cells from normal respiratory epithelium led to a significant upregulation of SSTR2 expression." (PMID 33402692, 2021). "In summary, this comprehensive analysis of SSTR2 expression in 402 primary, local recurrent and metastatic NPC patient samples established a highly significant association with EBV infection and suggest a key role for this receptor in this tumor (positive in >80% of samples)." (PMID 33402692, 2021). "We next explored a possible relationship of EBV infection and SSTR2 expression." (PMID 33402692, 2021).
Fibroadenoma (1 paper, 2024). A benign tumor of the breast characterized by the presence of stromal and epithelial elements. "This study confirmed the SSTR2 expression pattern in fibroadenoma, with borderline and malignant subtypes of phyllodes tumours." (PMID 39767203, 2024). "The SSTR2 protein was observed in both phyllodes tumour and fibroadenoma." (PMID 39767203, 2024).
glomus tumor (1 paper, 2024). A rare benign or malignant mesenchymal neoplasm arising from cells that resemble the modified smooth muscle cells of the glomus body. "However, the focal rather than diffuse staining for SMA and the unique expression of SSTR2 were unusual features that argued against a glomus tumor." (PMID 39720383, 2024).
Granuloma (1 paper, 2024). A compact, organized collection of mature mononuclear phagocytes, which may be but is not necessarily accompanied by accessory features such as necrosis. "Interestingly, the most prominent IHC staining for SSTR2 was, in the current study, found in the presence of multinucleated giant cells, which are the hallmark of GCM, but can also be found in noncaseating granulomas of patients with CS." (PMID 39518342, 2024).
Graves disease (1 paper, 2025). Graves' disease is an autoimmune disorder that leads to overactivity of the thyroid gland (hyperthyroidism).It is caused by an abnormal immune system response that causes the thyroid gland to produce too much thyroid hormones. "However, one patient developed Graves’ disease, potentially due to the expression of SSTR2 in the thyroid gland, indicating it may be an organ at risk during PRRT." (PMID 41304857, 2025).
Graves ophthalmopathy (1 paper, 2019). An autoimmune disorder of the EYE, occurring in patients with Graves disease. "Somatostatin receptors, especially SSTR-2 and SSTR-5 subtypes, with high affinity for octreotide are found in retro-ocular muscles and retrobulbar fat of Graves’ ophthalmopathy." (PMID 31463594, 2019).
Hashimoto thyroiditis (1 paper, 2020). An autoimmune disorder caused by the production of autoantibodies against thyroid tissue. "68Ga-DOTATOC, a somatostatin analog that predominantly targets SSTR-2 and SSTR-5 has demonstrated increased uptake in five of eight cases of Hashimoto’s thyroiditis." (PMID 33551992, 2020).
head and neck squamous cell carcinoma (1 paper, 2022). A squamous cell carcinoma that arises from any of the following anatomic sites: lip and oral cavity, nasal cavity, paranasal sinuses, pharynx, larynx, and salivary glands. "While one HPV-positive sinonasal carcinoma also showed patchy SSTR2 staining, the remaining HPV-positive sinonasal carcinomas, HPV-positive oropharyngeal squamous cell carcinomas, or oral cavity head and neck squamous cell carcinomas did not reveal any significant SSTR2 staining." (PMID 35198446, 2022).
heart failure (1 paper, 2023). Inability of the heart to pump blood at an adequate rate to meet tissue metabolic requirements. "This indicates that imaging the biological processes associated with integrin αvβ3 and SSTR2 expression could lead to improved monitoring of heart failure patients in treatment." (PMID 36673078, 2023).
hemangioblastoma (1 paper, 2021). "Regarding SSTR2, one case of neurofibroma and all cases of schwannoma, solitary fibrous tumor/hemangiopericytoma and hemangioblastoma were negative, while the other case of neurofibroma was positive." (PMID 34830858, 2021).
large-cell NEC (1 paper, 2024).
laryngeal carcinoma (1 paper, 2016). Carcinoma that arises from the laryngeal epithelium. "This study indicated that SSTR2 promoter hypermethylation was associated with the risk and progression of laryngeal cancer in males." (PMID 26796520, 2016). "Our results provided a clue for further studies on the role of SSTR2 in laryngeal carcinogenesis, and future studies were needed to confirm its potential as a biomarker for early diagnosis, therapy and prognosis of laryngeal cancer." (PMID 26796520, 2016). "Previous laryngeal cancer study has shown that the overall pattern of SSTRs expression is with high levels of SSTR1, “loss” of SSTR2 and intermediate levels of SSTR5." (PMID 26796520, 2016). "Our results provided a hypothesis that the SSTR2 methylation might be involved in the metastasis and invasion of laryngeal cancer." (PMID 26796520, 2016). "In light of previous findings, we aimed to test whether SSTR2 promoter methylation contributed to the pathogenesis of laryngeal cancer." (PMID 26796520, 2016). "However, there was a lack of association study between SSTR2 methylation and laryngeal cancer." (PMID 26796520, 2016).
liver fibrosis (1 paper, 2018). "Accordingly, strategies targeting the COX-2/SSTR-2 signaling pathway are postulated to either promote liver fibrosis by reducing hepatic inflammation or improve liver fibrosis by inhibiting the epithelial-to-mesenchymal transition of hepatocytes." (PMID 30038293, 2018).
lung fibrosis (1 paper, 2024). "Additionally, a single-cell proteomics study showed that pericytes are the most strongly associated cells with SSTR2 in lung fibrosis in inflammatory lung diseases." (PMID 39767203, 2024).
meningothelial tumors (1 paper, 2021). "The attempts to relate SSTR2 to tumor grade have been unsuccessful, despite the findings of higher SSTR2 expression in meningothelial tumors and in tumors with high microvascular density." (PMID 34830858, 2021).
mucoepidermoid carcinoma (1 paper, 2023). A carcinoma morphologically characterized the presence of cuboidal mucous cells, goblet-like mucous cells, squamoid cells, cystic changes, and a fibrotic stromal formation. "An examination of a collective of malignant salivary gland tumors using immunohistochemistry indicates that some tumors, such as the mucoepidermoid carcinoma, also exhibit SSTR2." (PMID 37568733, 2023). "In this study, of two cases of mucoepidermoid carcinoma, one had moderate SSTR2 expression and one had no SSTR2 expression." (PMID 37568733, 2023).
multiple myeloma (1 paper, 2023). "We have launched a phase-II trial to assess SSTR2 expression by 68Ga-DOTATATE PET/CT in symptomatic relapsing and refractory multiple myeloma patients (SCARLET trial—NCT04379817)." (PMID 37190261, 2023).
Myocardial fibrosis (1 paper, 2024). "However, recent findings indicate that SSTR subtype 1 and SSTR2 might be upregulated in areas with myocardial fibrosis." (PMID 39518342, 2024).
nesidioblastosis (1 paper, 2023). "Some years ago, somatostatin receptor scintigraphy (Octreoscan/111In-pentetreotide scintigraphy; mainly targets Somatostatin receptor type 2 [SSTR2]) and 18F-DOPA PET were successfully used to detect focal nesidioblastosis." (PMID 37371827, 2023).
oligoastrocytoma (1 paper, 2015). A WHO grade II tumor composed of a conspicuous mixture of two distinct neoplastic cell types morphologically resembling the tumor cells in oligodendroglioma and diffuse astrocytoma. "We found that SSTR2 staining was not restricted to oligodendroglial tumor cells but was similarly present in astrocytic cells in mixed oligoastrocytomas." (PMID 25977882, 2015).
oncocytoma (1 paper, 2024). "The oncocytoma demonstrated no SSTR2 expression and yet it showed a weak tracer uptake." (PMID 39123352, 2024).
ovarian carcinoma (1 paper, 2016). A malignant neoplasm originating from the surface ovarian epithelium. "Furthermore, recent studies have found that the expression of SSTR2 in ovarian cancer tissue is quite high and SSTA has the capacity to inhibit and reverse paclitaxel resistance from multiple pathways." (PMID 27825139, 2016). "We have also detected that A2780/Taxol paclitaxel-resistant human ovarian cancer cell expresses SSTR2 and therefore, the synthetic POC could exert its functions in a dose and time-dependent manner via its specific binding to cell surface." (PMID 27825139, 2016). "Our previous study in vitro using the human ovarian cancer cell line found that paclitaxel-resistant cancer cells express high levels of SSTR2, and POC treatment could lead to more cell apoptosis when compared to cells treated with paclitaxel alone." (PMID 27825139, 2016).
ovarian tumor (1 paper, 2016). "As in previous study, the high level expression of SSTR2 in xenografted paclitaxel-resistant ovarian tumor was confirmed by IHC, RT-PCR and western blot." (PMID 27825139, 2016).
Pancytopenia (1 paper, 2025). An abnormal reduction in numbers of all blood cell types (red blood cells, white blood cells, and platelets). "This likely explains why SSTR2-antagonists caused pancytopenia in clinical trials despite safe dosimetry estimates." (PMID 40521188, 2025).
periodontal disease (1 paper, 2019). "Since SST has antiproliferative, antiangiogenetic, and proapoptotic effects, our findings suggest that SSTR2 might play a critical role in periodontal diseases." (PMID 30609928, 2019). "Deciphering the regulation of SSTR2 might be important for a better understanding of the aetiopathogenesis of periodontal diseases." (PMID 30609928, 2019). "Although the present study suggests a potential role of SSTR2 in the aetiopathogenesis of periodontal disease, we have not examined the actions of SST itself and the regulation of other SSTRs." (PMID 30609928, 2019).
periodontitis (1 paper, 2019). An acute or chronic inflammatory process that affects the tissues that surround and support the teeth. "In addition, the periodontitis-associated microorganisms F. nucleatum induced a significant increase in SSTR2 expression by 6.4-fold and this stimulatory action of F. nucleatum was observed over a wide range of concentrations." (PMID 30609928, 2019). "By contrast, SSTR2 was found to be downregulated in a rat lipopolysaccharide-induced periodontitis model." (PMID 30609928, 2019). "As expected, the SSTR2 expression in gingival biopsies from sites of periodontitis was significantly higher than that in healthy biopsies." (PMID 30609928, 2019). "SSTR2 expressions in human gingival biopsies from sites of periodontitis were significantly higher than those in healthy biopsies." (PMID 30609928, 2019). "In a rat experimental periodontitis model, we also investigated the time course of SSTR2 expression in gingival biopsies." (PMID 30609928, 2019). "Taken together, our in-vitro and in-vivo results suggest a potential role of SSTR2 in the aetiopathogenesis of periodontitis." (PMID 30609928, 2019). "In order to validate our in-vitro findings in a more complex environment, we also studied the SSTR2 expression in human biopsies from periodontally healthy subjects and from periodontitis patients." (PMID 30609928, 2019). "Since SST has been shown to be antiproliferative, antiangiogenetic, and proapoptotic, our study suggests that SSTR2 might play a critical role in the aetiopathogenesis of periodontitis." (PMID 30609928, 2019). "Similarly, SSTR2 expression levels were also significantly enhanced at periodontally-diseased sites in a rat model of experimental periodontitis." (PMID 30609928, 2019). "Similarly, SSTR2 expression levels were significantly enhanced at periodontally-diseased sites in rat experimental periodontitis." (PMID 30609928, 2019). "Therefore, human biopsies from periodontally-healthy and periodontitis sites were obtained and, subsequently, analyzed for potential differences in the SSTR2 expression and protein levels by RT-PCR and immunohistochemistry." (PMID 30609928, 2019).
prediabetes (1 paper, 2020). "Our staining of Sstr2, together with other studies in human islets from obese donors, suggests that hyperglucagonaemia in prediabetes is not due to a reduction in SSTR2 protein." (PMID 32446876, 2020).
rectal cancer (1 paper, 2021). A primary or metastatic malignant neoplasm that affects the rectum. "Besides CXCL1, CXCL2, and CXCL3, we mined seven other hub genes related to rectal cancer, including SAA1, AGT, GNG4, SST, SSTR2, GAL, and CXCL12." (PMID 34269159, 2021). "In addition, three hub genes, including SST, SSTR2, and CXCL12, were significantly downregulated in the rectal cancer tissues." (PMID 34269159, 2021).